BRAF (B-Raf proto-oncogene, serine/threonine kinase)
Diseases named in the same sentence as BRAF in open-access papers (continued):
Sharing a sentence is not in itself a finding about the gene and the disease.
Lynch syndrome (continued). "As BRAF mutations are not observed in tumors from patients with Lynch syndrome, we cannot exclude that MSI/BRAF wild-type samples in the present series are from clinically undetected Lynch syndrome patients." (PMID 21103049, 2010). "Therefore, the presence of the BRAF V600E variant in tumor tissue almost excludes the possibility of Lynch syndrome in cases where MMR-IHC reveals loss of expression of both the MLH1 and PMS2 proteins." (PMID 41214301, 2026). "However, BRAF mutations are not found in Lynch syndrome, where microsatellite instability arises through a different mechanism involving germline mutations in mismatch repair genes." (PMID 39119381, 2024). "However, of late, the presence of a BRAF V600E mutation has also been found in patients with Lynch syndrome; therefore, its presence should not exclude germline testing if clinically indicated." (PMID 38957326, 2024). "Patients whose tumors demonstrate absent expression for any of the four mismatch repair proteins and no BRAF V600E variant are contacted by a genetic counselor to discuss the potential concern for Lynch syndrome and offered an appointment for consideration of genetic testing." (PMID 39238026, 2024). "Furthermore, the V600E mutation in BRAF (v-Raf murine sarcoma viral oncogene homolog B1) in MSI-high CRC with methylation of MLH1 promoters is associated with poor prognosis and decreased likelihood of Lynch syndrome." (PMID 37667167, 2023). "Similarly, the presence of a history of Lynch syndrome or the BRAF or KRAS mutation did not seem to affect response to immunotherapy." (PMID 32090113, 2020). "BRAF mutation is also reported to rule out Lynch syndrome, which may be of help to the clinicians in counseling the patients and their families." (PMID 28953975, 2017). "Methylation of the MLH1 promoter and BRAF V600E mutations are frequently detected in sporadic MSI-H CRCs but not in patients with Lynch syndrome, suggesting that testing for BRAF mutations and MLH1 promoter methylation may help differentiate Lynch syndrome from sporadic MSI-H/dMMR CRC." (PMID 36618386, 2022). "Lynch-like syndrome (LLS) patients develop LS-associated neoplasms (in particular CRC) but do not carry constitutional variants in MMR genes, or somatic BRAF mutations or MLH1 hypermethylation in CRCs43 they develop." (PMID 41419736, 2025). "BRAF mutation is reported in sporadic CRC with hypermethylated phenotype, but not in hereditary CRC such as Lynch syndrome." (PMID 36819812, 2022). "Because most sporadic dMMR CRCs exhibit MLH1 promoter methylation and many also have BRAF mutations, MLH1 promoter methylation analysis can be used to discriminate sporadic tumors from Lynch syndrome in patients without BRAF mutations." (PMID 36618386, 2022). "Germline testing would not be excluded on the basis of MLH1 hypermethylation or BRAF V600E for individuals with a personal and/or family history suggestive of Lynch syndrome." (PMID 34397043, 2021). "BRAF pathogenic variants are not common in sporadic endometrial cancers; thus, BRAF testing is not helpful in distinguishing endometrial cancers that are sporadic from those that are Lynch syndrome related." (PMID 34118983, 2021). "A patient had suspected Lynch syndrome (case 16): One had 2 first-degree relatives with CRC, and developed CRC before 50 years, which had dMMRs but not the BRAF mutation; their MMR gene germline mutations were not investigated." (PMID 33031197, 2020).
Lynch syndrome (continued). "Objective responses were observed regardless of PD-L1 expression, BRAF and KRAS mutation status, or the presence of Lynch syndrome." (PMID 28635639, 2017). "On the other hand, germline MMR genetic testing was not done in patients with MMR deficiency to confirm Lynch syndrome; for MLH1-deficient cases, we ruled out CIMP-associated tumors by analyzing the V600E BRAF mutation and MLH1 methylation status." (PMID 23049789, 2012). "If a BRAF mutation is found in dMMR/MSI tumors, Lynch syndrome can mostly be ruled out." (PMID 40171464, 2024). "Among all patients with CRC who had a loss of MLH1/PMS2 with BRAF V600E or MLH1 promoter hypermethylation, 2 of 16 were ultimately found to have a pathogenic germline mutation, but neither of these patients had Lynch syndrome, with one having an increased risk allele for prostate cancer." (PMID 37509234, 2023). "Testing for BRAF, MLH1 promoter methylation and MMR germline genes along with detection of microsatellite instability can distinguish between sporadic CRC or genetic disorders such as Lynch syndrome.This study found that in 502 CRC samples, there were 64 (12.7%) patients with MSI-H." (PMID 37427134, 2023). "National Comprehensive Cancer Network (NCCN) guidelines recommend BRAF testing to distinguish between sporadic MLH1 deficient tumors caused by promoter methylation with associated BRAF mutations and loss of MLH1 expression in Lynch syndrome tumors by germline mutation and absence of BRAF mutations." (PMID 26252492, 2015). "Current ESMO, NICE (UK), and Australian guidelines do not recommend routine BRAF testing in non-metastatic CRC patients, except in MSI-H CRC to distinguish between sporadic and familial (Lynch syndrome) cases." (PMID 34940086, 2021). "BRAF and promoter methylation are usually conducted in patients with a lack of MLH1 protein to eliminate the possibility of Lynch syndrome." (PMID 29849630, 2018).
brain tumors (102 papers, 2012 to 2025). "Out of 135 brain tumor samples tested, 28 (20.7%) had one clinically relevant variant, 11 (8.1%) had a BRAF Val600Glu variant, 14 (10.3%) had an IDH1 Arg132 variant, and 3 (2.2%) had an IDH2 Arg172 variant." (PMID 37483495, 2023). "The oncogenic BRAF V600E somatic mutation frequently found in epilepsy-associated pediatric brain tumors arises during early brain development and causes intrinsic epileptogenicity in developing neurons." (PMID 36233759, 2022). "A prime example for the successful implementation of targeted therapies in brain tumors are BRAF V600E mutations in PCPs." (PMID 35864412, 2022). "Recently, the molecular markers of CD34 and BRAF mutation were interestingly found to be associated with brain tumors with epilepsy, especially GNT3–7." (PMID 36307486, 2022). "Genomic analysis of human cancers detected BRAF mutations in a high portion of various solid tumors, including brain tumors." (PMID 36077798, 2022). "We determine BRAF mutational status with a sensitivity of 80% and specificity of 100% in the plasma of patients with brain tumors." (PMID 33799709, 2021). "Co‐occurrence of BRAFV600E and CDKN2A loss defines a subset of pediatric brain tumors that are responsive to combined treatment with BRAF and CDK4/6 inhibitors." (PMID 33769711, 2021). "BRAF mutations, particularly the V600E mutation and KIAA1549-BRAF fusions, are also present in a significant subset of primary brain tumors." (PMID 35155453, 2021). "The BRAF V600E mutation has been identified as a key driver in brain tumors and brain tumor metastasis." (PMID 33799709, 2021). "The BRAF V600E mutation and KIAA1549-BRAF fusion are alterations found in several brain tumors and show a distinct prognostic impact in some entities." (PMID 31181803, 2019). "In the following section we provide an overview of BRAF mutations in common adult brain tumors and their potential therapeutic implications." (PMID 31181803, 2019). "Activating BRAF-V600E mutations are recurrently found in pediatric glial and glioneuronal brain tumors and specific inhibitors are entering clinical trials." (PMID 30818875, 2019). "While class II and III BRAF mutations are found in primary brain tumors, further research is necessary to determine their sensitivity to third-generation RAF inhibitors and/or MEK inhibitors." (PMID 31466300, 2019). "In this review, we present the spectrum of BRAF mutations and fusion alterations present in each class of primary brain tumor based on publicly available databases and publications." (PMID 31466300, 2019). "By exploiting a nicely constructed Cre/lox animal model Robinson and colleagues were able to demonstrate that the combination of BRAF mutation with Akt activation or Ink4a/ARF loss is required to generate brain tumors with high-grade appearance." (PMID 31181803, 2019). "Emerging evidence support the effectiveness of targeted therapies for brain tumors with BRAF V600E mutation." (PMID 31345255, 2019). "BRAF mutations, particularly the V600E mutation and KIAA1549–BRAF fusions, are present in a significant subset of primary brain tumors." (PMID 31466300, 2019). "High throughput analyses with this antibody followed and revealed that BRAF V600E mutations are less frequent in adults, compared to pediatric brain tumors." (PMID 31181803, 2019). "The V600E mutated variant of BRAF disrupts auto-inhibition, leading to constant activation of cell growth and has been identified in various types of pediatric brain tumors." (PMID 30443293, 2018). "An evaluation of additional patient samples with verified BRAF mutations allowed assessment of the effectiveness of this approach in other brain tumor types." (PMID 28094001, 2017). "Particularly, in a pediatric brain tumor with BRAF mutation, hydroxycholoroquine was able to reverse acquired resistance to BRAF inhibitor." (PMID 28445132, 2017). "The patient’s resected brain tumor is BRAF V600E mutated, NRAS wild type (WT), and TERT C250T mutated." (PMID 26597176, 2015).
brain tumors (continued). "This case suggests that a drug of this class can penetrate a primary brain tumor and affect a primary CNS lesion harboring a BRAF mutation." (PMID 24725538, 2014). "These translational studies will inform the next generation of clinical trials of BRAF V600E inhibitors and radiation in patients with BRAF V600E-mutated brain tumors and metastases." (PMID 23717811, 2013). "In one study of 27 pediatric grade I and II pediatric brain tumors, the frequency of BRAF V600E mutation was queried using an oligonucleotide microarray, and 14 of 31 tumors (40%) were found to encode the BRAF V600E mutation." (PMID 23717811, 2013). "Among primary brain tumors, activating BRAF point mutations are found frequently in pleomorphic xanthoastrocytoma (60 – 70%) and ganglioglioma (~ 20%) and less frequently in pilocytic astrocytomas." (PMID 22385786, 2012). "Recent studies have identified alterations in the BRAF serine/threonine kinase gene as the likely causative mutation in these childhood brain tumors." (PMID 22548077, 2012). "Activating mutations in BRAF are frequent in certain subtypes of pediatric brain tumors." (PMID 39510293, 2024). "The distribution of BRAF alterations (most commonly the V600E variant) in adult brain tumors spans across biologically and clinically diverse entities and may have prognostic and therapeutic implications." (PMID 37124503, 2023). "Furthermore, pediatric brain tumors tend to be genetically very different from adult brain tumors, featuring alterations, like histone mutations in high-grade gliomas (HGGs) or BRAF molecular alterations in PA." (PMID 37509316, 2023). "Our results confirm the real world benefits of BRAF mutation-targeted therapies in brain tumors." (PMID 35864412, 2022). "It should be noted that targeted approaches with BRAF inhibitors could provide fruitful options in other BRAF V600E mutated brain tumors such as the aggressive or rapidly progressive papillary craniopharyngioma and rhabdoid meningioma meningioma." (PMID 35267432, 2022). "A tumour’s molecular signature may in some instances give the rationale for targeted therapy, as BRAF-targeted therapy has shown positive response in certain brain tumours with BRAF V600 mutation." (PMID 35879477, 2022). "BRAF alterations are a hallmark of different rare primary brain tumours." (PMID 34360713, 2021). "Primary brain tumors with BRAF mutations can have a good response to BRAF MEK inhibitors (BRAF MEKi), and there may be a synergistic response when combined with autophagy inhibitors." (PMID 31748891, 2020). "This supports the hypothesis that autophagy inhibition can make brain tumors with BRAF mutations more chemosensitive to BRAF inhibition." (PMID 31748891, 2020). "This may explain the relatively high frequency of BRAF mutant brain tumors associated with favorable outcome." (PMID 31181803, 2019). "BRAF mutations in brain tumors have also been assessed in recent years." (PMID 27454254, 2016). "BRAF V600E-mutations have been described in a modest 6% to 7% of primary central nervous system (CNS) tumors, but with increased prevalence in the pediatric population and in certain brain tumor subtypes." (PMID 24725538, 2014). "Testing for the presence of BRAF V600E mutation may be relevant in clinical neuropathology practice for the following reason: BRAF mutations affect some brain tumors (both primary and secondary) and small molecule drugs specifically inhibiting the mutated BRAF protein have been developed." (PMID 22385786, 2012). "Several critical genes in the MAPK signaling pathway, including BRAF, FGFR, and NF1, are mutated in brain tumors." (PMID 41323387, 2025). "Currently approved BRAF inhibitors demonstrate limited efficacy against brain tumors and are ineffective for those with BRAF fusions." (PMID 40430547, 2025).
brain tumors (continued). "Utilizing live analysis of nanopore sequencing data, we evaluated the brain tumor-associated molecular markers IDH1 R132, IDH2 R172, pTERT C228 and C250, H3F3A K27 and G34, Hist1H3B K27, and BRAF V600." (PMID 39606159, 2024). "The prognostic significance of BRAF V600E mutation and KIAA1549-BRAF fusion appears to be dependent on the histological type of the primary brain tumor, the age of diagnosis, and the tumor location." (PMID 37124503, 2023). "When we analyzed the somatic mutations of genes related to brain tumor development, such as ARTX, BRAF, and MGMT, we identified more mutations in the PDX samples than in the original tumors." (PMID 38001935, 2023). "Although alteration of the BRAF and MAPK pathway causes brain tumors, targeting therapies are now recognized as potential novel treatment approaches." (PMID 37675821, 2023). "Fusions involving B-raf proto-oncogene, serine/threonine kinase (BRAF) are subtypes of oncogenic BRAF genetic abnormalities that have been reported in certain cases of brain tumors, such as pilocytic astrocytomas." (PMID 38066633, 2023). "Collectively, our review reveals the specific role of BRAF mutations as a major molecular driver in PLGG and HGG gliomagenesis, impacting the parallel progression and prognosis of those brain tumors." (PMID 36831610, 2023). "mTOR pathway activation is thought to be one of the main mechanisms of resistance in BRAF V600E-mutant brain tumors following targeted treatment." (PMID 35159037, 2022). "Currently, the data on the effect of BRAF inhibitors (BRAFi) on BRAF V600E-positive brain tumors are limited to a few experimental studies and case reports; thus, there is a high demand for further investigation." (PMID 35130969, 2022). "The aim of this study was to develop an assay for the detection of BRAF V600E in the plasma of patients with brain tumors and brain tumor metastasis." (PMID 33799709, 2021). "The most frequent fusion and single nucleotide mutation observed in brain tumours are KIAA1549:BRAF and BRAF V600E, respectively, even if a vast range of rarer alterations has been recognised." (PMID 34360713, 2021). "Growing attention has been devoted to design tailored therapies with MAPK-inhibitors in brain tumours with BRAF activation, with particular regard to paediatric low-grade gliomas (PLGGs)." (PMID 34360713, 2021). "This strategy of combining autophagy inhibition with BRAF inhibition monotherapy in brain tumors was demonstrated in several brain tumors, including PXAs, using chloroquine." (PMID 31748891, 2020). "Like many other neoplasms, brain tumors, especially the ones originating from glia of white and grey matter, can harbor v-raf murine sarcoma viral oncogene homolog B1 (BRAF) gene alterations." (PMID 31181803, 2019). "Treatment with first-line BRAF selective inhibitors such as vemurafenib or dabrafenib should be avoided in brain tumors with BRAF fusions." (PMID 31181803, 2019). "With the development of BRAF targeted inhibitors, the role of BRAF alterations in adult brain tumors was further investigated." (PMID 31181803, 2019). "Autophagy inhibition overcomes multiple mechanisms of resistance to BRAF inhibition in brain tumors." (PMID 30443293, 2018). "Current consensus in the literature indicates that patients with BRAF mutant brain tumors should receive a BRAF inhibitor or combinatorial therapy with BRAF and MEK co-inhibition." (PMID 29179523, 2017). "We report here that targeting a completely different process, autophagy, can overcome multiple BRAF inhibitor resistance mechanisms in brain tumors." (PMID 28094001, 2017). "Berghoff AS, Preusser M: BRAF alterations in brain tumours: molecular pathology and therapeutic opportunities." (PMID 27454254, 2016).